GDPD5 (glycerophosphodiester phosphodiesterase domain containing 5)
Description:
Ecto-phospholipase that cleaves the phosphodiester bond in the glycosylphosphatidylinositol (GPI) anchor of various proteins, releasing them from the plasma membrane into the extracellular space. Cleaves the GPI-anchor of glypican-6/GPC6, thereby positively regulating neuron differentiation in a cell-autonomous manner. May also hydrolyze the GPI-anchor of glypican-3/GPC3. Cleaves the GPI-anchor of the serine protease inhibitor RECK, leading to its inactivation. RECK inactivation inhibits NOTCH signaling in neighboring cells and induces differentiation of spinal motor neurons (By similarity). RECK inactivation can also regulate amyloid-beta precursor protein (APP) processing by ADAM10. May additionally catalyze the hydrolysis of the phosphodiester bond in sn-glycerol 3-phosphocholine, potentially contributing to osmotic regulation of cellular glycerophosphocholine levels (By similarity).
Synonyms: GDE2; PP1665
Tractability: Antibody: UniProt predicts a signal peptide or a membrane-spanning region; its Gene Ontology location is reachable by antibodies, with medium confidence. PROTAC: ubiquitination databases record sites on it; its protein half-life has been measured.
Gene: Protein-coding gene on chromosome 11 (75,434,638 to 75,525,985, reverse strand). Ensembl gene ENSG00000158555.
Subcellular location: Cell membrane; Membrane raft; Cell projection, growth cone
Subcellular location (Human Protein Atlas): Golgi apparatus
Pathways (Reactome):
Metabolism: Glycerophospholipid catabolism
Gene Ontology:
Molecular function: phospholipase activity; protein binding; glycerophosphocholine phosphodiesterase activity; glycerophosphodiester phosphodiesterase activity; phosphatidylinositol-4,5-bisphosphate phospholipase C activity; phosphoric diester hydrolase activity
Biological process: negative regulation of amyloid precursor protein biosynthetic process; negative regulation of amyloid-beta formation; positive regulation of neuron differentiation; lipid metabolic process; negative regulation of Notch signaling pathway; positive regulation of cell cycle; positive regulation of cell differentiation
Cellular component: plasma membrane; plasma membrane raft; endomembrane system; axon; growth cone; membrane; membrane raft; neuronal cell body; perinuclear endoplasmic reticulum
Genetic constraint (gnomAD): Loss-of-function variants: 49 observed, 70.44 expected, observed/expected ratio (o/e) 0.7, 90% interval 0.55 to 0.88. The upper end of that interval is the gene's LOEUF score, 0.88, which puts it in group 3 of 6, group 1 being the genes least tolerant of losing a copy. Missense variants: 690 observed, 801.86 expected, observed/expected ratio (o/e) 0.86, 90% interval 0.81 to 0.92. Synonymous variants: 332 observed, 328.74 expected, observed/expected ratio (o/e) 1.01, 90% interval 0.92 to 1.11.
Homologues: Orthologues: chimpanzee GDPD5 (99% identical), macaque GDPD5 (98% identical), pig GDPD5 (91% identical), guinea pig GDPD5 (91% identical), mouse Gdpd5 (91% identical), rat Gdpd5 (90% identical), rabbit GDPD5 (89% identical), dog GDPD5 (87% identical), zebrafish gdpd5b (58% identical), zebrafish gdpd5a (49% identical). Paralogues in human: GDPD2 (37% identical), GDPD4 (32% identical), GDE1 (10% identical), GDPD1 (9% identical), GDPD3 (9% identical).
Diseases named in the same sentence as GDPD5 in open-access papers:
GDPD5 is named in the same sentence as 24 diseases in open-access papers, as found by Europe PMC text mining. Sharing a sentence is not in itself a finding about the gene and the disease. The quoted sentences say what the papers report.
breast carcinoma (7 papers, 2014 to 2022). "It was found that GDPD5 knock-down inhibits breast cancer cell proliferation, migration, and invasion." (PMID 36038558, 2022). "It was reported that silencing of GDPD6 increased the GPC levels more than GDPD5 silencing, suggesting this as a potential treatment strategy for breast cancer." (PMID 38715862, 2021). "High-resolution 1H MRS analysis of breast cancer cell lines in which GDPD5 or GDPD6 were silenced demonstrated that GDPD6 has a leading role in regulating the intracellular GPC level in breast cancer cells." (PMID 28083512, 2016). "For example, in aggressive ER− breast cancers, GDPD5, PLD1, and ChKα, were simultaneously highly expressed, leading to elevated PC and tCho levels." (PMID 28083512, 2016). "GDPD5 expression was found to correlate with breast cancer malignancy." (PMID 28083512, 2016). "This suggests that GDE3/GDPD5 may serve as a marker of clinical outcome in breast cancer." (PMID 28849762, 2017). "In another study, authors used targeted silencing of two glycerophosphodiesterase genes, GDPD5 and GDPD6 by small interfering RNA (siRNA) for studying choline and phospholipid metabolism in MDA‐MB‐23 and MCF‐7 cell lines of breast cancer." (PMID 38715862, 2021). "siRNA silencing of GDPD5 reduced the viability and migration of ER + MCF-7 breast cancer cells, and decreased the migration and invasion of triple-negative MDA-MB-231 breast cancer cells." (PMID 28083512, 2016). "GDPD5, as well as PLD1 and ChKα, were highly expressed in estrogen receptor negative (ER−) breast cancers, which also displayed higher PC, tCho, and lower GPC in comparison with ER+ cases." (PMID 28083512, 2016).
neuroblastoma (7 papers, 2017 to 2023). Neuroblastoma (NB) is the most common solid, extracranial childhood tumor. "Overexpression of GDE2/GDPD5 in neuroblastoma and SH-SY5Y neuronal cells facilitates the release of GPC6 and decreases the surface level of GPC6." (PMID 34301723, 2021). "It is biologically proved that GDPD5 is involved in lipid metabolism, migration and proliferation of NB, providing preliminary evidence for the complex biological function and immune regulation of GDPD5 involved in lipid metabolism in neuroblastoma." (PMID 36430219, 2022).
colorectal cancer (5 papers, 2021 to 2026). A primary or metastatic malignant neoplasm that affects the colon or rectum. "Circ_0007142 is overexpressed in colorectal cancer and targets glycerophosphodiester phosphodiesterase domain containing 5 (GDPD5) through binding to miR-874-3p, triggering the onset of ferroptosis and thus inhibiting the progression of colorectal cancer." (PMID 37152286, 2023). "GDPD5 was found to be overexpressed in colorectal cancer (CRC) and to promote metastasis and chemoresistance." (PMID 34950701, 2021).
breast tumors (1 paper, 2017). "The glycerophosphodiester phosphodiesterase domain containing 5 (GDPD5), which encodes for the enzyme glycerophosphocholine phosphodiesterase that catalyzes the degradation of GPC to free choline has been found to be positively correlated with PCho, tCho and PCho/GPC levels in human breast tumors." (PMID 28509845, 2017).
colon cancer (1 paper, 2021). "Moreover, downregulation of GDPD5 and SOD2 by these miRs or by small interfering RNAs also reverse EMT in colon cancer cell lines in vitro." (PMID 33429840, 2021).
pemphigus (1 paper, 2025). Pemphigus is a group of rare autoimmune diseases that cause blistering of the skin and mucous membranes (mouth, nose, throat, eyes, and genitals).This conditioncan occur at any age, but often strikes people in middle or older age. "Differential expression analysis was conducted to investigate the expression patterns of the five genes (XBP1, FBXO45, SAT2, AIFM1, and ACSL4) and eight other DEGs associated with ferroptosis (G3BP1, WBP11, TET2, IRF8, FASN, GDPD5, H1-4, and HUWE1) in both the pemphigus and control groups." (PMID 40612574, 2025).
tumor (7 papers, 2016 to 2023). "Based on these results, GDPD5 will qualify as a potential tumor-suppressor gene." (PMID 36430219, 2022). "MiR-874-3p targets glycerophosphodiester phosphodiesterase domain containing 5 (GDPD5), and the upregulation of GDPD5 reverses the miR-874-3p-triggered tumor inhibition and ferroptosis promotion." (PMID 37065473, 2023). "The downregulated genes GDPD5, NXPH1, and AHI1 were identified as tumor suppressors, while the upregulated genes CPLX3 and SPAG6 were regarded as oncogenes." (PMID 34950701, 2021). "The upregulated genes CPLX3 and SPAG6 appeared to be associated with poor survival, whereas the downregulated genes GDPD5, NXPH1, and AHI1 were identified as tumor suppressors." (PMID 34950701, 2021). "Additionally, LINC00922 silencing enhanced the inhibitory effect of DDP on tumor growth, whereas reversing the effects of DDP on LINC00922, miR-874-3p and GDPD5 expressions in tumors." (PMID 35282764, 2022).
cancer (4 papers, 2010 to 2022). A tumor composed of atypical neoplastic, often pleomorphic cells that invade other tissues. "To further explore the biological function of GDPD5, we overexpressed GDPD5 in the human SH-SY5Y cell line and then examined the changes in its metabolism, as well as the migration and proliferation behavior of cancer cells." (PMID 36430219, 2022). "It has been reported that miR-195 suppresses the proliferation, migration, invasion and radiosensitivity of cancer cells through directly targeting some oncogenes, including CARM1, YAP, GDPD5 and WNT3A." (PMID 30487160, 2018).
GDPD5 also shares sentences with these, for which no sentence is quoted: neurodegenerative disease (7 papers); amyotrophic lateral sclerosis (3); Alzheimer disease (2); amyloid (1); Anxiety (1); Cardiovascular Disease (1); dengue (1); gastric cancer (1); hearing loss (1); hereditary spastic paraplegia (1); memory impairment (1); motor neuron degeneration (1); nasopharyngeal carcinoma (1); osteosarcoma (1); Parkinson disease (1); spinal muscular atrophy (1).